KRAS (KRas proto-oncogene, GTPase)
Diseases named in the same sentence as KRAS in open-access papers (continued):
Sharing a sentence is not in itself a finding about the gene and the disease.
tumor (continued). "Previous reports have shown that miR-326 might serve as a tumor suppressor via KRAS or TWIST1 suppression in solid cancers." (PMID 33741523, 2021). "Our objective was to confirm that PDAC cells surviving genetic ablation of KRAS retain their tumorigenic capacity, to identify stages of tumor progression when KRAS is essential, and to reveal signaling nodes in the KRAS pathway that are responsible for tumor maintenance." (PMID 33674596, 2021). "KRAS also activates the hexosamine biosynthesis pathway and the non-oxidative arm of the pentose phosphate pathway to promote the increase in glycolysis, and to support tumor cell viability." (PMID 34680229, 2021). "Furthermore, we show that the RAS degrader suppressed the increase in RAS level observed in response to selective inhibition, and potently inhibited KRAS(G12C)-driven tumor growth in a mouse xenograft model." (PMID 33976200, 2021). "Our data also show that trifluridine-tipiracil is the preferred third-line treatment option for patients with mCRC regardless of their age, KRAS mutation status, tumor sidedness, comorbidities, or previous tolerability issues." (PMID 34199694, 2021). "KR12 also induced significant tumor growth suppression in xenograft models, with low host toxicity in KRAS-mutated but not wild-type tumors, thus representing a promising agent against RAS mutated CRC with encouraging pre-clinical data." (PMID 34944853, 2021). "Based on experiences with the spontaneous KRAS tumor models, there was a need to apply alternative approaches to express mutant KRAS from its endogenous locus specifically in pancreatic progenitors and their more differentiated descendants in the exocrine pancreas." (PMID 34491463, 2021). "KRAS-mutant tumors are characterized by large amount of neoantigens, and as such they are faced with the need to tackle the immune response mediated by tumor-specific T cells in order to sustain their growth." (PMID 33494181, 2021). "The mean survival time was shorter among patients with KRAS mutations than among patients with wild type KRAS tumours (54.46 vs. 58.02 months), but the difference was not statistically significant (P = 0.444)." (PMID 33979337, 2021). "In addition, it was reported that extracellular KRAS protein released by ferroptotic tumor cells and taken up by macrophages contributes to M2 macrophage polarization, thus, resulting in the development of pancreatic tumor cells." (PMID 34239619, 2021). "KRAS mutations are the most frequent mutations in PDAC, present in 90–95% of tumours." (PMID 33445669, 2021). "The prognostic relevance of sex, age, ASA grade, BMI, preoperative CEA level, tumor location, tumor size, histologic grade, LVI, number of retrieved lymph nodes (LNs), AJCC stage, MSI, KRAS mutation status, NLR, TLR, BLR, and SNR was assessed in the survival analysis." (PMID 34108552, 2021). "The analysis was performed by pooling the efficacy of CT plus an anti-EGFR agent crossover to CT plus an anti-VEGF agent, versus CT plus an anti-VEGF agent crossover to CT plus anti-EGFR agent on the OS of patients with KRAS-WT who had different tumor localization." (PMID 34768686, 2021). "KRAS signaling induces in tumor cells the expression of immunomodulatory factors and inflammatory cytokines, with subsequent recruitment of neutrophils and myeloid-derived suppressor cells (MDSCs), creating an immunosuppressive tumor microenvironment." (PMID 33777798, 2021). "Increased nuclear expression of RB1 [RB1(N)↑], CDH3(C)↑-STK17A(N)↑ and FLNA(C)↑-KRAS(C)↑were associated with survival, but not independent of tumor stage, where C and N denote cytoplasm and nucleus, respectively." (PMID 33936170, 2021). "It is unclear whether glutaminase inhibitors like BPTES, CB-839 and compound 968, exert their anticancer effects by modulating ferroptosis sensitivity in KRAS tumor cells and how glutamine dependency might be a predictive marker of ferroptosis susceptibility." (PMID 34485382, 2021).
tumor (continued). "However, when in combination with a MEK inhibitor, GDC-0994 exhibited enhanced anti-tumor efficacy in KRAS-mutant CRC cell lines." (PMID 34742312, 2021). "Additionally, KRAS mutant NSCLC secreted a specific cytokine profile with neutrophil recruitment into the tumour micro-environment, resulting in a pro-hypoxic condition." (PMID 34298636, 2021). "Furthermore, mutant KRAS also promotes metabolic deregulation and alterations in the tumor microenvironment." (PMID 34680229, 2021). "Likewise, CD44v5-6 and CD44v8-9, but not CD44s, are significantly increased in non-small cell lung adenocarcinoma and mediate tumour cell proliferation and poor prognosis by activating the KRAS/MAPK signalling pathway." (PMID 34944493, 2021). "In Case No. 5, both tumors showed codon 12 KRAS mutation (12Ala in the index tumor and 12Val in the companion tumor)." (PMID 33671994, 2021). "KRAS mutant tumors present a high glucose metabolism, so that, multiple glycolytic genes are upregulated and its suppression could prevent tumor growth." (PMID 35096591, 2021). "Responses to treatment were observed only in individuals with wild type KRAS tumours." (PMID 33979337, 2021). "In all these cases, the KRAS G12C mutation emerged at PD, although was not previously detected in the primary tumor tissue." (PMID 34943432, 2021). "Although additional KRAS mutations were identified in two patients, none had more than one activating KRAS mutation in tumor DNA." (PMID 34298235, 2021). "In addition, downstream effector molecules of KRAS signaling pathways were shown to differ according to tumor type." (PMID 33982211, 2021). "There were no KRAS or NRAS mutations with indices higher than the cut-off values in DNA purified from pretreated primary tumor cells." (PMID 34840814, 2021). "Knocking down ELF3 expression attenuates activation of NF-κB pathway genes in two LUAD cell lines A549 (KRAS mutation) and NCI-H1975 (EGFR mutation L858R), supporting the conclusion that inflammatory cytokines (e.g. IL1B) can regulate tumor cell proliferation and anti-apoptosis through ELF3 action." (PMID 33144684, 2021). "CIMP-high CRCs are associated with distinct clinicopathological and molecular features such as older age, female preponderance, proximal tumor location, higher grade, reduced COX-2 expression, increased frequency of TGFBR2 mutations, and high rate of MSI, KRAS, and BRAF mutations." (PMID 33652647, 2021). "The in vivo function of KRAS-Mφ to CRC progression was determined through tumor xenograft models." (PMID 33833221, 2021). "However, the WES analysis of KRAS and NRAS mutations in AT-1 and AT-2 suggests that both serial sister cell lines consist of two clones from the primary tumor." (PMID 34940123, 2021). "On RNA-sequencing, neither PI3KCA nor KRAS mutational status were associated with the benefit of aspirin use or tumor downstaging." (PMID 33430037, 2021).
tumor (continued). "Based on the observed synergy between BRAF and MYC, we surmise that distinct MYC targets may enhance KRAS-induced tumor growth via reversible immune suppression." (PMID 33674596, 2021). "Furthermore, KRAS driver mutations lead to the activation of Wnt and MAPK pathways, which controls tumour cell proliferation, motility, metabolism and survival." (PMID 33452856, 2021). "In addition, dual targeting of miR-21 (anti-miR-21) and KRAS (siKRAS or mimic-217) packaged into the tumor-penetrating NPs decreased tumor growth in in vivo models generated from PANC-1 and D8-175 PDAC cell lines." (PMID 33923200, 2021). "Other signatures were also identified in this analysis that implicates previously unreported processes in Vκ*MYC disease biology including signatures related to knockdown of the tumour suppressor TCF21, KRAS mutations, and constitutive activation of the RHOA oncogene." (PMID 34732728, 2021). "Ultimately, the tumor stratification is necessary for the success of the KRAS directed therapies." (PMID 34944853, 2021). "We also found a significantly higher proportion of women with KRAS mut tumours compared to men." (PMID 34503114, 2021). "Furthermore, an upregulation of stress granules protects tumor cells against further stress stimuli, including chemotherapeutic agents in mutant KRAS tumor cells." (PMID 34359663, 2021). "While some tumour neoantigens are recurrent among cancer entities (e.g. KRAS position 12 mutations), the overall molecular fingerprint of a cancer is unique in every patient irrespective of tumour type." (PMID 33824481, 2021). "Considering the effect of KRAS mutations on tumor microenvironment, we analyzed the prognostic significance of KRAS mutation types after adjusting for the tumor-infiltrating lymphocytes (TIL) and tumor-stromal percentage (TSP) statuses." (PMID 34272423, 2021). "The tumour microenvironment (TME) may change in response to cancer treatments such as KRAS G12C inhibition, with potential implications for combination therapies." (PMID 34625563, 2021). "Wild-type KRAS organoid lines of HCC were sensitive to the EGF receptor inhibitor AZD8931, while organoids harboring mutated KRAS were resistant, suggesting guidance for personalized medicine based on tumor heterogeneity." (PMID 34520134, 2021). "Importantly, in patients who had tumour biopsies performed before and after the initiation of cetuximab, this observation of initially wild-type KRAS tumours acquiring a resistant phenotype and becoming mutant KRAS was reproduced." (PMID 34272358, 2021). "Since IHC analysis did not identify tumour cells as a source of SAA, the acquisition of mutations such as KRAS does not appear to directly stimulate increased expression of SAA by transformed tumour cells." (PMID 34203378, 2021). "Of note, there is a possibility that other factors induced by KRAS may synergize with each other to engineer permissive microenvironmental conditions for tumor growth and metastasis." (PMID 33833221, 2021). "But, patients with wild-type KRAS tumours can be treated with bevacizumab or anti-EGFR therapy." (PMID 34557315, 2021). "For example, speaking about tumour tissue, one would expect to capture signals from KRAS mutations, especially in non-resectable cancer (nrPC), which includes metastasis patients." (PMID 34071263, 2021). "Interestingly, after heterozygous conversion of 27 of the KRAS rare codons to more optimal codons, KRAS levels are elevated and this is accompanied by reduced tumour formation and senescence induction." (PMID 34584217, 2021).
tumor (continued). "Data here displayed places vitamin C as an unexpected capital inhibitor of tumor metabolism in KRAS mutant CRC, regulating the expression of PDK-1 and, therefore, the activity of the PDHC complex, boosting the conversion of pyruvate into Acetyl CoA within the mitochondria." (PMID 33664850, 2021). "This might be one of the reasons that autophagy is important for sustaining the survival and proliferation of KRAS-mutant tumours." (PMID 32929194, 2021). "However, given higher expression of oncogenic KRAS drives increased tumour growth in transformed cells, it seems that a mechanism to increase its protein synthesis would be required once the barrier of oncogene induced senescence is overcome." (PMID 34584217, 2021). "It is, therefore, possible that the high incidence of KRAS mutations in PDAC is the reason why EGFR has never been found mutated in this kind of tumor." (PMID 34440587, 2021). "Overall, these results suggest that the probability of acquiring a particular KRAS allele was not significantly greater in tumor samples that did obtain the KRAS mutation." (PMID 33753749, 2021). "H&E staining along with quantification of human HPRT mRNA expression confirmed that co-injection with KRAS-Mφ or siMOCK-Mφ could lead to a significant increase in the tumor burden of liver metastasis." (PMID 33833221, 2021). "The tumor tissues were subjected to whole exome sequencing (WES) and four mutations with potential clinical significance were identified: CDKN2A deletion, CDK6 amplification, PIK3CA amplification, and KRAS G12V mutation." (PMID 34327143, 2021). "Therefore, BI-3406 reduces cell proliferation and suppresses tumor growth in vivo xenograft models of KRAS-driven cancers." (PMID 34830024, 2021). "Notably, tumor cells show negligible apoptosis by KRAS depletion in 2D culture, but become highly dependent on KRAS in 3D culture or in vivo." (PMID 34680229, 2021). "Nevertheless, despite the use of highly sensitive technology, circulating KRAS mutation detection does not perfectly reflect the mutation burden of the primary tumor from which it originated." (PMID 34742312, 2021). "These assays allow identification and quantification of mutated KRAS directly from circulation without previous knowledge of tumor KRAS mutational status, which is not routinely tested for resectable PDACs." (PMID 33430810, 2021). "Indeed, a recent study has reported that the co-inhibition of SHP2 and KRAS in xenograft models is effectively able to suppress feedback reactivation of KRAS pathway, producing a significant tumor shrinkage." (PMID 35004317, 2021). "Furthermore, oncogenic KRAS promotes macropinocytosis to transport extracellular proteins as an amino acid source for the TCA cycle to sustain tumor growth." (PMID 34680229, 2021). "Furthermore, although AZD8835 and AZD5363 were efficient in reducing tumor progression, the use of AZD8835 further inhibited the activation of BRCA1/2 mRNA expression in KRAS-mutated cell lines." (PMID 34680390, 2021). "The multivariable regression model without 3D-QAM yielded tumor diameter and KRAS mutation as 1-year ASR predictors." (PMID 34868968, 2021). "Importantly, these cells are recruited and reprogrammed by PDAC cells during tumor initiation, driven largely by oncogenic KRAS signaling emanating from PDAC cells." (PMID 34771644, 2021).
tumor (continued). "The majority of PDAC cells harbor KRAS mutations which further enable tumor cells to survive under stress conditions like the lack of oxygen through stabilization of Hypoxia Inducible Factors (HIFs)." (PMID 34376225, 2021). "Tumor burden, adjuvant chemotherapy and response to first-line CT according to KRAS evolution." (PMID 33854968, 2021). "For NSCLC in particular, different studies have shown that TMB in the primary tumour tends to be higher in men than in women and is also positively correlated with tobacco consumption, KRAS, and BRAF mutated tumours, whereas the presence of ROS1 and ALK rearrangements is linked to lower TMB." (PMID 34683113, 2021). "Although they possess this immunogenic substrate which could sensitise to immunotherapy, oncogenic KRAS is capable of inducing an immunosuppressive tumour microenvironment, thus preventing optimal response to checkpoint blockade." (PMID 34200676, 2021). "TheraScreen KRAS kit (Qiagen), a test based on amplification refractory mutation system (ARMS) technology, is the first clinically validated and FDA-approved kit widely used to evaluate tumor-specific mutations in patients with CRC." (PMID 34742312, 2021). "H/FPC cases were mainly KRAS mutation negative and harbored tumor specific mutations that are potential treatment targets in the clinic." (PMID 33807330, 2021). "In this regard, circulating tumor DNA (ctDNA) can act as a genomic surrogate for tumor and has been investigated as an early diagnostic biomarker for PDAC, given that >90% of tumors harbor a KRAS mutation." (PMID 34503206, 2021). "In addition, concomitant blockade of MEK and KRAS exhibits synergistic anti-tumor effect in KRAS-mutant CRC, which can provide a theoretical basis for the combination of MEK inhibitors and KRASG12C covalent inhibitors in treating KRASG12C-mutant CRC." (PMID 34742312, 2021). "Other mechanisms of PD-L1 upregulation are overexpression of Myc along with mutated KRAS; activating mutations of EGFR, KRAS or JAK2; and CMTM4 and CMTM6 posttranslational regulation in tumor cells and DCs, in addition to other posttranscriptional modifications." (PMID 33322522, 2020). "One mechanism by which KRas activation disrupts this pathway could be altered calcium signaling activation by ROS, since tumor cells commonly have disrupted redox states." (PMID 33020304, 2020). "The identification that oncogenic KRas suppresses mechanically-induced calcium at the level of ROS provides a mechanism for how KRas could alter cell responses to tumor microenvironment mechanics and may reveal chemotherapeutic targets for cancer." (PMID 33020304, 2020). "In another study, GC1118 exhibited anti-tumor effects against gastric cancer irrespective of KRAS mutation." (PMID 33142709, 2020). "Moreover, we also found seven cases (N = 7/61, 11.5%) that were KRAS wild-type in tumor tissue and KRAS mutant in plasma." (PMID 33233668, 2020). "Although this is limited to one patient, results are in-line with a recent study suggesting that EGFR-mutated NSCLC patients with KRAS mutations detected in tumor before the start of treatment do not benefit from EGFR TKIs." (PMID 33520716, 2020). "Therefore, we exploit this KRAS-specific macrodrug to demonstrate that KRAS ablation can be an attractive way to target any mutant KRAS-expressing tumour." (PMID 32591521, 2020). "The result suggests that in the presence of DTT, the KRAS mutant epitope shows a higher Anti-Tumor efficacy than any other non-mutated epitope." (PMID 32903495, 2020). "We further describe how long-term survival was achieved with sequential resections of both primary and recurrent tumors in the liver and lung, which showed identical KRAS mutations with no other mutations identified among the main tumor suppressor genes." (PMID 32569179, 2020). "The multivariate SH model identified the absence of surgery, higher tumor stage and grade, and unmarried status as risk factors for both KRAS MT and KRAS WT CRC patients (HR > 1, p < 0.05)." (PMID 32547859, 2020).